TNF (tumor necrosis factor)
Diseases named in the same sentence as TNF in open-access papers (continued):
Sharing a sentence is not in itself a finding about the gene and the disease.
diabetic nephropathy (continued). "Numerous studies have demonstrated that tumor necrosis factor-α (TNF-α), MCP-1 and interleukin-1β (IL-1β) participate in different inflammatory states associated with renal diseases, including ischaemia/reperfusion injury, kidney transplantation, diabetic nephropathy and hypertensive renal damage." (PMID 27129290, 2016). "TNF-α may promote renal damage in diabetic nephropathy through several mechanisms." (PMID 25587544, 2014). "Previous studies have shown that the levels of serum proinflammatory factors such as tumour necrosis factor-α (TNF-α) and interferon-γ (IFN-γ) in diabetic nephropathy patients were higher than those in healthy subjects." (PMID 40824899, 2025). "In preclinical models, UA has been shown to lower inflammatory cytokines such as IL-6, TNF-α, and MCP-1 in diabetic kidney disease." (PMID 41374004, 2025). "TNF-α inhibitors were reported to have positive effects on diabetic peripheral neuropathy (DPN) and diabetic nephropathy in diabetic animal models." (PMID 38776022, 2024). "About another inflammatory cytokine—TNF-alpha- MCD model podocytes initially demonstrated higher levels of that cytokine, which was found previously elevated in a rat model of diabetic nephropathy." (PMID 37543700, 2023). "In STZ-induced diabetic nephropathy mice, APF also decreased the mRNA and protein expression of inflammatory factors such as TNF-α, IL-1-β, and IL-6, and also improved the damage of high glucose to renal mesangial cells by regulating autophagy." (PMID 37101717, 2023). "Many inflammatory cytokines, including interleukin-1 (IL-1), interleukin-8 (IL-8), interleukin-6 (IL-6), and tumor necrosis factor (TNF), play an important role in the development and progression of diabetic nephropathy." (PMID 37398707, 2023). "Another study based on ursolic acid reported that immunohistochemical staining revealed a rise in the expression of cytokines such as TNF-α, MCP-1, and IL-1β in diabetic nephropathy rats compared to control animals." (PMID 38202711, 2023). "Reduction in:-TNF-α production;-NF-κB and TGF-β levels in diabetic nephropathy;-TGF-β, VCAM-1, and NF-κB expression, and ROI’s production;-left ventricular hypertrophy and fibrosis." (PMID 35163696, 2022). "Various inflammatory stimuli, such as TNF-α, CCL-2, IL-1β, and IL-6, which drive chronic renal inflammation in diabetic kidney disease, have been shown to stimulate Saa3 production in mice." (PMID 35055081, 2022). "TNF-alpha is a cytokine that induces inflammatory processes and cell death, modulates immune responses; furthermore, TNF-alpha blockade ameliorates diabetic nephropathy in rats." (PMID 36289848, 2022). "It has been proved that the TNF signaling pathway is connected with cholesterol-dependent podocyte apoptosis and albuminuria, which may be primarily activated immediately in the process of various NS progression, including diabetic nephropathy and focal segmental glomerulosclerosis." (PMID 35837376, 2022). "In this regard, TNF-α drives the activation of profibrotic cytokine TGF-β and accumulation of extracellular matrix in diabetic nephropathy." (PMID 35966094, 2022). "The purpose of the current study was to evaluate the role of oxidative markers AOPP, AGEs, MDA antioxidant GSH and inflammatory biomarkers IL-6, TNF-α, and MPO in diabetic nephropathy compared to controls and type 2 diabetics." (PMID 36363561, 2022). "For instance, inhibiting the levels of inflammatory cytokines including IL-6, IL-1b, and TNF-α in PRAT through upregulation of heme oxygenase system reduced renal inflammation and ameliorated diabetic nephropathy in rats." (PMID 34298949, 2021). "Another study reported the co-administration of coenzyme Q10 and sitagliptin suppression of TNF-α, TGF-β in renal tissue on experimentally induced diabetic nephropathy in rats." (PMID 34064322, 2021).
diabetic nephropathy (continued). "Another study reported that the KD of miRNA-21 using a specific inhibitor of it decreased the expression levels of pro-inflammatory cytokines such as IL-1β and TNF-α, and alleviated kidney damage in STZ-induced diabetic nephropathy rats." (PMID 33193581, 2020). "Inflammatory cytokines, such as IL-1β and TNF-α, and chemokines, including MCP-1 and ICAM-1, have been shown to contribute to the development of diabetic nephropathy." (PMID 30841605, 2019). "In another study, kaempferol attenuated diabetic nephropathy in NRK-52E and RPTEC cells via suppressing RhoA/Rho-kinase mediated pro-inflammatory signaling (i.e., TNF-α, IL-1β, and TGF-β1)." (PMID 31480505, 2019). "Inflammatory cytokines including TNF-α and MCP-1 take part in inflammatory responses of renal diseases including hypertensive renal damage, diabetic nephropathy, and ischemia/reperfusion injury." (PMID 30598687, 2018). "The main action pathways closely related to the development of diabetic nephropathy were the TGF-β1, AMPK, insulin, TNF-α, and lipid metabolism pathways as per network pharmacology analysis." (PMID 29853965, 2018). "The inhibitory effects on the levels of interleukin-2, interleukin-6, interleukin-10, and tumor necrosis factor-α in serum and kidney revealed the protection of PHC against diabetic nephropathy." (PMID 27034961, 2016). "Inflammatory cytokines including TNF-α, MMP-9, and COX-2 lead the deterioration of diabetic nephropathy." (PMID 27212945, 2016). "Inflammatory mediators including TNF-α and COX-2 play important roles in the pathogenesis of diabetic nephropathy." (PMID 24991534, 2014). "Wulingsan alleviates the progression of Diabetic Nephropathy by its multiple active ingredients acting synergistically on key targets such as SRC, AKT1, and TNF, thereby regulating PI3K-Akt and MAPK signaling pathways to inhibit inflammation, oxidative stress, and fibrosis." (PMID 40800999, 2025). "The study found important targets, including TNF, CREB1, and PTGS2, indicating that CR-C1 may be important in lowering oxidative stress and inflammation in diabetic nephropathy." (PMID 40435181, 2025). "In the context of diabetic nephropathy, enalapril inhibited the TNF-α mRNA expression in the renal cortex and decreased both the renal and urinary TNF-α concentrations, correlating with reduced albuminuria and suggesting a protective effect against inflammation-induced renal damage." (PMID 40722848, 2025). "in different diabetic populations did not support these previous results; they did not observe any marked difference in the serum TNF‐α concentration between patients with diabetic nephropathy and patients without diabetic nephropathy." (PMID 40804707, 2025). "Moreover, coriander plays a useful role in the management of diabetic complications, particularly alleviating diabetic nephropathy and neuropathy through the inhibition of AGE formation, inhibition of TNF-α release, and reduction of oxidative stress." (PMID 39519546, 2024). "Tripterygium glycosides is proved to not only regulate inflammatory factors such as TNF-α, IL-1β and TGF-β1, but also ameliorate podocyte injury and glomerular hypertrophy, reduce urinary protein in rats with diabetic nephropathy through anti-inflammation and inhibition of macrophage infiltration." (PMID 39898319, 2024). "Also, high concentrations of TNF-α and the activated IL-17 signaling pathway have been shown to play an essential role in STZ-induced diabetic corneal epithelium and diabetic nephropathy." (PMID 38529047, 2024). "It has been determined that inflammation markers such as tumor necrosis factor alpha (TNF-α) and IL-1β could predict the progression of diabetic nephropathy." (PMID 37189380, 2023).
diabetic nephropathy (continued). "In a study involving hemodialysis patients with diabetic kidney disease, the activity of the antioxidant enzymes catalase (CAT), superoxide dismutase (SOD), and glutathione peroxidase (GSH-Px) was assessed, and IL-6 and TNF-α levels were determined as an indicator of oxidative stress." (PMID 36615736, 2022). "Transplantation of MSCs (mesenchymal stromal cells) into rats with diabetic nephropathy significantly reduced the levels of CD103+CDC1s, while decreasing the expression of inflammatory factors TNF-alpha and MCP-1, which in turn attenuated renal injury through the inactivation of CD8+ T cells." (PMID 36385487, 2022). "The nephroprotection of fucoidan nanoparticles appears to be related to the antioxidative stress that suppresses MDA and increases SOD and GPx expression and the anti-inflammatory effect that decreases IL-6 and TNF-α, which can further decrease BUN and creatinine levels in diabetic nephropathy." (PMID 35685736, 2022). "Tumor necrosis factor-α is an essential mediator of inflammation that can induce renal vasoconstriction, which is a potential mechanism of nonproteinuric diabetic nephropathy." (PMID 35413081, 2022). "Neither TNF-α nor IL-6 are related to the KYN/Trp ratio, but TNF-α is associated with the KYN level, indicating inflammatory system activation in diabetic nephropathy." (PMID 34617264, 2022). "In addition, IL-6, TNFα, and MPO levels were also increased in case of diabetes nephropathy compared to controls." (PMID 36363561, 2022). "One possible explanation is that, because TNFR levels are at least 100 times greater than TNF-α levels, circulating TNFRs play an important role in the progression of diabetic kidney disease, regardless of the TNF-α levels." (PMID 32130282, 2020). "Using TNF as predictive marker and TGFB1 and EDN1 as monitoring markers might be a valuable strategy finding the subset of diabetic nephropathy patients benefitting the most from tacrolimus treatment." (PMID 28060893, 2017). "Moreover, TNF-α has also been reported to contribute to the pathogenesis of other forms of CKD – for example, diabetic nephropathy, Alport glomerulosclerosis, and chronic ischemic renal injury." (PMID 28927419, 2017). "Inflammatory cytokines such as IL-1β, IL-18, TNF-α, MCP-1, and ICAM-1 are significantly increased in renal tissues during diabetic nephropathy and attenuating the expression of these cytokines may protect against diabetic renal injury." (PMID 26881256, 2016). "In a rodent model of DM and diabetic nephropathy, MSC treatment ameliorated diabetic nephropathy via inhibition of MCP-1 expression by secreting HCP, thus reducing macrophage infiltration and down-regulating Il-1β, IL-6, and TNF-α expression in the renal tissue of diabetic rates." (PMID 24936198, 2014). "Altered expressions of (miR-122-5p, miR-486-5p, and miR-21-5p) in diabetic nephropathy suggest their involvement in these processes, while the selected inflammatory markers (IL-6, TNF-α, CRP) mediate DKD-related inflammation." (PMID 41318413, 2025). "Moreover, vitamin D is essential for protecting kidney function through reducing 24 h urine protein and inflammatory status (CRP, TNF- α, IL-6) in patients with diabetic nephropathy, but without effects on eGFR." (PMID 36900141, 2023). "GLP-1 RAs downregulated the expression of tubulointerstitial tumor necrosis factor alpha (TNFα), monocyte chemoattractant protein-1(MCP-1), collagen I, alpha-smooth muscle actin (α-SMA), and fibronectin (FN) which are all reported to play a role in the diabetic nephropathy." (PMID 31757028, 2019). "This pathway may implicate inflammatory biomarkers with shorter half-life, such as interleukin-6, TGF-β, and TNF-α, because studies have shown that Tocovid reduced serum creatinine and ameliorated diabetic nephropathy through downregulation of TGF-β and TNF-α in diabetic rats." (PMID 30227659, 2018).
diabetic nephropathy (continued). "However, it would be very interesting to investigate whether the correlation between TNF-alpha and ACR persists in patients with various stages of diabetic nephropathy." (PMID 25587544, 2014). "In the rat mesangial cells induced by high glucose and tumor necrosis factor-α (TNF-α), the total flavonoids of lychee seed distinctly decreased the protein expression of TGF-β1, FN, and Col IV, which indicated the total flavone might improve the diabetic nephropathy fibrosis process." (PMID 34690773, 2021). "Therefore, to investigate whether the activation of TNFα related caspase 8 and t-Bid (cleaved form of Bid) has any role in STZ-induced diabetic nephropathy and whether mangiferin can inhibit these activations; immunoblot analysis has been carried out using appropriate antibodies." (PMID 25233093, 2014).
epilepsy (221 papers, 2010 to 2026). A brain disorder characterized by episodes of abnormally increased neuronal discharge resulting in transient episodes of sensory or motor neurological dysfunction, or psychic dysfunction. "A TNF-α increase in limbic structures in response to seizure activity was found in animal models, and in some studies, elevated levels of TNF-α in epilepsy patients were associated with higher severity of the disease." (PMID 41154178, 2025). "Understanding the interplay between NFκB, IL‐1β, and TNF‐α not only sheds light on the mechanisms underlying epilepsy but also opens avenues for identifying potential therapeutic targets." (PMID 41523603, 2025). "A related study found that higher levels of IL-6 and TNF-α in the serum were closely related to increased susceptibility to epilepsy." (PMID 39858450, 2025). "With the activation of astrocytes, the influential pro-inflammatory cytokine IL-1β induces the generation of IL-6 and TNF-α, both of which are strongly linked to epilepsy." (PMID 39598325, 2024). "Epidemiological research has shown that a variety of circulating bioactive factors are associated with epilepsy, including macrophage colony-stimulating factor, interleukin-1β, and tumor necrosis factor-α." (PMID 39259090, 2024). "Elevated levels of IL‐1β, IL‐6, IL‐9, and TNF‐α have been linked to the subsequent onset of epilepsy in children who experienced acute seizures." (PMID 38361811, 2024). "We identified over 100 genes with significantly altered expression after 4AP treatment, including multiple genes involved in MAPK, TNF, and neuroinflammatory signaling pathways, all of which have been linked to epilepsy previously." (PMID 38664009, 2024). "In particular, IFN-γ and TNF-α, two pro-inflammatory cytokines that we found to be elevated in the parietal cortex of mice subjected to surgery, have been linked to epilepsy." (PMID 39062548, 2024). "Many studies have shown that inflammation is associated with the development of epilepsy, and RA is an autoimmune inflammatory disease in which upregulation of the inflammatory cytokines TNF-α, IL-1, and IL-6 is closely related to pathogenesis." (PMID 38817604, 2024). "TNF-α also plays a pro-inflammatory role and mice with excessively high levels of this cytokine are at high risk of epilepsy." (PMID 38078329, 2023). "TNF-α has been shown to be associated with epilepsy, with Liu demonstrating elevated serum TNF-α levels." (PMID 35054141, 2022). "In vivo studies also proved that activated glial cells produce large amounts of proinflammatory cytokines such as TNF-α, IL-1β, and IL-6, which, in turn, cause neuronal damage in the hippocampus of rats with epilepsy." (PMID 35456948, 2022). "High levels of systemic TNF have been associated with epilepsy, particularly with drug-resistant epilepsy." (PMID 35598439, 2022). "It is known that ILF3-AS1 potentiates inflammatory cytokines and TNF-alpha expression together with increased matrix metalloproteinases, all of which are associated with epilepsy." (PMID 35328484, 2022). "The high level of tumor necrosis factor associated with the inflammatory response after stroke is an important cause of poststroke epilepsy." (PMID 33959658, 2021). "In epilepsy, the activation of NF-κB in microglia has been known to cause neuroinflammation by inducing pro-inflammatory cytokines and chemokines (TNF-α, IL-1β, MIP-1α, and MCP-1)." (PMID 34680566, 2021). "LPS-stimulated astrocytes can be present during inflammatory response (promote IL-1β, IL-6, and TNF-α expression) and be used to mimic epilepsy-inflammation to assess the underlying molecular or cellular mechanisms." (PMID 33776905, 2021). "Many studies have confirmed that high concentrations of pro-inflammatory cytokines, such as tumor necrosis factor alpha (TNFα), can cause neuronal degeneration and hyperexcitability in epilepsy." (PMID 35069411, 2021).